DLX5 (distal-less homeobox 5)
Diseases named in the same sentence as DLX5 in open-access papers (continued):
Sharing a sentence is not in itself a finding about the gene and the disease.
thymic lymphomas (3 papers, 2010 to 2021). "Subsequent transgenic mouse experiments revealed that forced expression of Dlx5 in immature T-cells using a Lck promoter (Lck-Dlx5 mice), also induced thymic lymphomas." (PMID 34203994, 2021). "In any case, the collective findings indicate that Lck-Dlx5-driven lymphomagenesis differs from that of Lck-MyrAkt2-driven thymic lymphoma formation." (PMID 28122332, 2017). "Lck-Dlx5 mice from each of four founders developed thymic lymphomas with high penetrance, and all tumors retained expression of Myc-tag Dlx5." (PMID 28122332, 2017). "The lack of relationship with Ki67 expression indicates that in this model the expression of DLX5/6 is independent also from cell proliferation, though previous data indicated that Dlx5 contributes to increased cell proliferation in mouse thymic lymphomas." (PMID 21108812, 2010). "Moreover, transgenic mice overexpressing Dlx5, specifically in immature T-cells, develop spontaneous thymic lymphomas." (PMID 34203994, 2021).
depression (2 papers, 2022 to 2024). "D7S821 polymorphism linked to depression could therefore involve alterations in DLX5/6 locus expression." (PMID 39120293, 2024). "Variants in the DLX5/6 regulatory network could be implicated in the predisposition to depression and in the variability of patients’ response to antidepressant treatment." (PMID 39120293, 2024). "Deletions in the regulatory sequences of DLX5/6 often result in a complex syndrome that include craniofacial defects and split hand–foot malformations due to altered DLX5/6 developmental expression in the limbs; it can be associated with episodes of depression." (PMID 39120293, 2024). "Gadd45b intervenes in depression by modifying the DNA methylation levels of GAD67, recombinant neurotrophic tyrosine kinase receptor type 2 (Ntrk2), neurturin, and distal-less homeobox 5 (Dlx5)." (PMID 36311022, 2022).
Ectrodactyly (2 papers, 2016 to 2023). A condition in which middle parts of the hands and/or feet (digits and meta-carpals and -tarsals) are missing giving a cleft appearance. "The limb and facial malformations observed in Dlx5/6 double mutant mice are similar to those observed in split hand foot malformation type I (SHFM1, MIM 183600), a clinically and genetically heterogeneous human ectrodactyly." (PMID 37124614, 2023).
Hearing impairment (2 papers, 2016 to 2025). A decreased magnitude of the sensory perception of sound. "Beyond NR2F1 and DLX5/6, our map offers a general platform for investigating enhancer-driven mechanisms in hearing loss." (PMID 41169613, 2025). "This high-resolution view allowed us to identify enhancer-promoter interactions at critical loci, including NR2F1 and DLX5/6, both of which are linked to hearing loss." (PMID 41169613, 2025). "The red SHFM-HL tracks overlap with two prominent chromatin loops, reinforcing the hypothesis that these enhancer regions physically interact with the Dlx5/6 locus in cochlear chromatin and that their disruption may impact chromatin architecture in a region linked to hearing loss." (PMID 41169613, 2025). "Genomic studies in SHFM1 patients have shown that the severity of hearing impairment correlates with the location and size of the chromosomal breakpoint within the 7q21.3 region, which determines how much of the DLX5/6 regulatory landscape is affected." (PMID 41169613, 2025). "We focused on two cochlea disease-linked regions, NR2F1 and DLX5/6, because disease-associated structural variants overlap their loop anchors, providing an opportunity to examine how disruptions at these sites could reshape chromatin organization and impair gene regulation in hearing loss." (PMID 41169613, 2025). "Further supporting this mechanism, a pericentric inversion (chr7: 29,043,157–96,185,954) displaced DYNC1I1 exons 15 and 17 nearly 67 Mb away from DLX5/6, preventing proper enhancer-promoter interactions and leading to SHFM1 and hearing loss." (PMID 41169613, 2025).
leukemia (2 papers, 2020 to 2021). A malignant (clonal) hematologic disorder, involving hematopoietic stem cells and characterized by the presence of primitive or atypical myeloid or lymphoid cells in the bone marrow and the blood. "Moreover, DLX5 hypermethylation was associated with lower rate of complete remission and shorter time of leukemia‐free/overall survival, and was also confirmed by Logistic/Cox regression analysis." (PMID 32508046, 2020). "Accordingly, we speculated that DLX5 may also be regulated by histone methyltransferase in the transformation from MDS to leukemia." (PMID 34409024, 2021). "The hypermethylation of DLX5 promoter is related to its low expression and represents a common event in AML and MDS, which also contributes to the transformation of MDS into leukemia." (PMID 34409024, 2021). "By quantitative polymerase chain reaction, we also validated that DLX5 hypermethylation was frequent event in both AML and MDS, and also correlated with MDS transformation to leukemia." (PMID 32508046, 2020). "Notably, DLX5 hypermethylation is reported to be a common event in AML and MDS, and also concerned with the transformation from MDS to leukemia." (PMID 34409024, 2021).
myelodysplastic syndrome (2 papers, 2021). A clonal hematopoietic disorder characterized by dysplasia and ineffective hematopoiesis in one or more of the hematopoietic cell lines. "Hypermethylation of the DLX5 gene occurs frequently in AML and myelodysplastic syndrome (MDS)." (PMID 34203994, 2021).
non-small cell lung carcinoma (2 papers, 2011 to 2021). A group of at least three distinct histological types of lung cancer, including non-small cell squamous cell carcinoma, adenocarcinoma, and large cell carcinoma. "The overexpression of the DLX5 gene in mammalian cellsstimulates cell proliferation and can beobserved in endometrial carcinoma, non-small cell lung cancer (NSCLC), and smallcell lung cancer." (PMID 22649693, 2011).
osteoporosis (2 papers, 2022 to 2023). A condition of reduced bone mass, with decreased cortical thickness and a decrease in the number and size of the trabeculae of cancellous bone (but normal chemical composition), resulting in increased fracture incidence. "The analysis of other mouse models, such as mice carrying conditional alleles of Dlx5 or Dlx5/6 in bone, will be decisive to evaluate the potential implication of these genes in osteoporosis." (PMID 36291143, 2022). "The osteoblast/osteoclast coupling associated with increased resorption activity in Dlx5−/− mutants could permit a better understanding of the origin of bone homeostasis-related diseases, such as osteoporosis or osteopenia, resulting from immobilization." (PMID 36291143, 2022). "Collectively, these observations prompt us to conclude that polymorphisms in SNPs regulating DLX5/6 expression are involved in BMD determination and might be considered susceptibility factors for osteoporosis." (PMID 36291143, 2022). "Therefore, we suggest that PUM2-mediated DLX5 regulation may be an important regulatory axis for osteogenic differentiation of human MSCs, and PUM2 could be a target for gene therapy to slow or prevent osteoporosis progression by modulating DLX5-mediated osteogenesis of MSCs." (PMID 37088847, 2023).
viral infections (2 papers, 2010 to 2023). "Characterization of the E12.5 telencephalon from wtShh and ShhN viral infections performed at E9.5 confirms that cortical tissue is ventralized, expressing Dlx2, Dlx5 and Evfc." (PMID 21114856, 2010).
Zinc deficiency (2 papers, 2010). A deficiency of the essential metal Zinc; an essential cofactor for many enzymes. "Dlx5 has been shown to induce expression of Runx2 in chicken, and Runx2, which is important for osteogenic differentiation, was recently found to be downregulated during zinc deficiency, and abnormally accumulated in osteoblasts from Slc39a13 null mice." (PMID 20937081, 2010). "Together these data suggest that zinc deficiency, caused by reduced zinc uptake or disruption of zinc transporters, leads to dysregulation of mineralising cells in a process that involves suppression of DLX5/6 expression and downstream effects on osteoblast differentiation." (PMID 20932299, 2010).
achondroplasia (1 paper, 2026). Achondroplasia is the most common form of chondrodysplasia, characterized by rhizomelia, exaggerated lumbar lordosis, brachydactyly, and macrocephaly with frontal bossing and midface hypoplasia. "Perturbations in these programs, exemplified by mutations in Fgfr3, Sox9, and Dlx5, underlie region-specific skeletal dysplasias, such as achondroplasia, campomelic dysplasia, and split-hand/foot malformation, demonstrating the lasting impacts of embryonic patterning errors." (PMID 41596573, 2026).
ameloblastoma (1 paper, 2025). The most common odontogenic tumor, arising from the epithelial component of the embryonic tooth and usually affecting the molar-ramus region of the mandible or maxilla. "In humans, Dlx5 has been expressed in ameloblastoma, the second most common odontogenic tumor." (PMID 40003710, 2025).
Arthritis (1 paper, 2024). Inflammation of a joint. "There is increasing evidence that DLX5 induces inflammation and is implicated in many pathogenic mechanisms and diseases, such as cancer, neurodevelopmental disorders, pregnancy syndrome, osteogenesis, and arthritis." (PMID 39539538, 2024).
atherosclerosis (1 paper, 2023). A disease characterized by the build-up of fatty material and calcium deposition in the arterial wall resulting in partial or complete occlusion of the arterial lumen. "Furthermore, in atherosclerosis and related morbidities, an increasing body of evidence suggests that oxidized LDL may regulate the SMC proliferation/apoptosis balance through miRNAs, as was recently proven for the miR-124-3p/DLX5 axis." (PMID 37570694, 2023).
cognitive deficits (1 paper, 2020). "The idea that GluN2D could be a viable therapeutic target is also supported by previous reports in Dlx5/6+/- mice, in which mPFC FSINs exhibited decreased functional properties that were associated with cognitive deficits in vivo, which were reversed with optogenetic stimulation of mPFC FSINs." (PMID 32497062, 2020).
COVID-19 (1 paper, 2025). A disease caused by infection with severe acute respiratory syndrome coronavirus 2. "The hypermethylated genes with lowest p-values for hospitalized COVID-19 patients at inclusion (T1) and at 6 weeks post-inclusion (T2) versus HCs included NXN, SLC2A12, RAD54L2, GIMAP5, and PPP2R5C, while the top five hypomethylated genes with lowest p-value were, LOC101928650, DLX5." (PMID 41227320, 2025).
deafness (1 paper, 2023). An inherited or acquired condition characterized by the complete loss of the ability to hear from one or both ears. "In this study, we identified through SNP array a de novo 7q21 deletion involving exons 15 and 17 of DYNC1I1, but not including DLX5/6, in a patient affected by SHFM, bilateral deafness and an abnormality of the inner ear." (PMID 37628577, 2023).
developmental delay (1 paper, 2021). "A study on humans has shown multiple individuals with deletion of DLX5 and DLX6 who had reported severe phenotypes including ectrodactyly, hearing loss, abnormal pinnae, cleft palate, lower jaw retrognathia, developmental delay and abnormal teeth." (PMID 33815981, 2021).
disc degeneration (1 paper, 2024). "In conclusion, MEL might reduce the degree of NP cell apoptosis and alleviate disc degeneration by inhibiting DLX5." (PMID 39539538, 2024). "Furthermore, RT–qPCR, Western blotting, and IHC were used to analyze patient samples, and we demonstrated that the expression level of DLX5 was positively correlated with the degree of disc degeneration." (PMID 39539538, 2024).
EEC syndrome (1 paper, 2016). EEC syndrome is a genetic developmental disorder characterized by ectrodactyly, ectodermal dysplasia, and orofacial clefts (cleft lip/palate). "Similarly, the mRNA level of DLX5, a p63-target gene that is associated with EEC syndrome, was enhanced by T4 and T11, 27- and 13-fold, respectively." (PMID 27195674, 2016).
endometriosis (1 paper, 2021). The growth of functional endometrial tissue in anatomic sites outside the uterine body. "Epigenetic alterations of a few genes (DLX5, CDKN1C, PTGER2, and GATA3) are common for endometriosis and obstetric complications." (PMID 34833476, 2021).
Failure to thrive (1 paper, 2022). Failure to thrive (FTT) refers to a child whose physical growth is substantially below the norm. "Despite appearing relatively normal at birth, the Dlx5 KCC2 cKO mice exhibited a severe failure to thrive phenotype at later ages." (PMID 35370549, 2022). "Nonetheless, the Dlx5 KCC2 cKO mice have failure to thrive and spontaneous seizures leading to early death around the third week of life." (PMID 35370549, 2022).
Guillain-Barre syndrome (1 paper, 2023). A spectrum of rare post-infectious neuropathies that usually occur in otherwise healthy patients. "DLX5 has been shown to be involved in the development of the olfactory system, and ZIKV has recently been associated with olfactory disorders in mice as well as reduced olfactory function in patients with ZIKV-induced Guillain-Barré syndrome." (PMID 37515107, 2023).
hypertrophic cardiomyopathy (1 paper, 2024). A condition in which the myocardium is hypertrophied without an obvious cause. "The results revealed that the pathways related to tumor progression, such as hypertrophic cardiomyopathy-related genes, the extracellular matrix-receptor interaction pathway, and the TGF-β signaling pathway, were significantly enriched in the high DLX5 expression group." (PMID 38760791, 2024).
Hypoglycemia (1 paper, 2022). A decreased concentration of glucose in the blood. "Though we observed a mild hypoglycemia in Dlx5 KCC2 cKO, blood glucose levels of Dlx5 KCC2 cKO remained higher than those reported to cause seizures." (PMID 35370549, 2022).
hypospadias (1 paper, 2019). Hypospadias is the displacement of the urethral meatus on the ventrum of the penis. "The anterior and posterior NTDs observed in Dlx5/6 mutant mice are also associated with hypospadias, characterized by midline urethral malformations, and limb ectrodactyly." (PMID 30889190, 2019).
Infertility (1 paper, 2022). "Simultaneous deletion of Dlx5 and Dlx6 in the postnatal uterus leads to alterations in uterine adenogenesis and infertility, suggesting that they act redundantly for epithelial morphogenesis in the uterus." (PMID 35909540, 2022).
intervertebral disc degeneration (1 paper, 2024). "As expected, immunohistochemical fluorescence staining and quantitative analysis revealed that DLX5 expression was significantly increased in the SDD of human tissue and that its expression level was positively correlated with the severity degree of intervertebral disc degeneration." (PMID 39539538, 2024).
Kallmann syndrome (1 paper, 2015). Kallmann syndrome (KS) is a developmental genetic disorder characterized by the association of congenital hypogonadotropic hypogonadism (CHH) due to gonadotropin-releasing hormone (GnRH) deficiency, and anosmia or hyposmia (with hypoplasia or aplasia of the olfactory bulbs).
keloid (1 paper, 2022). An irregularly shaped, elevated mark on the skin caused by deposits of excessive amounts of collagen during wound healing. "In terms of expression level, BMP4, MSX1, TBX2, SIX1, DLX5, and DLX2 were lowly expressed, while HAND2, IRX1, EDN1, and MEF2C were highly expressed in keloid fibroblasts." (PMID 35047146, 2022).
knee osteoarthritis (1 paper, 2022). "Here, we found that Dlx5, SP7, and BMP-2 were all increased in papain-induced knee osteoarthritis, and upregulation of SP7 and BMP-2 were partly dependent on Dlx5." (PMID 35280506, 2022).
lung adenocarcinoma (1 paper, 2023). A carcinoma that arises from the lung and is characterized by the presence of malignant glandular epithelial cells. "Among them, low expression of C12orf56, DLX5, DSC3, FEZF1, GSTA1, H2BC9, IGSF11 and high expression of EREG, CEACAM6, SLC34A2 in lung adenocarcinoma were found to predict poor prognosis for patients." (PMID 37035196, 2023).
lung squamous cell carcinoma (1 paper, 2023). "Ten prognostic beneficial factors of the heterogeneous expression of lung squamous cell carcinoma genes driven by TTN mutations were screened for and DLX5, FEZF1, H2BC9, EREG, and SLC34A2 were identified as the main factors of the prognostic models." (PMID 37035196, 2023).
macrodactyly (1 paper, 2020). "Our study suggested DLX5 as a potential biomarker for development of potential therapeutic treatment for macrodactyly." (PMID 32632138, 2020). "Our findings provide the theoretical basis for targeted therapy of macrodactyly by inhibiting key regulators such as PI3K and DLX5." (PMID 32632138, 2020).
mental disorder (1 paper, 2024). A disease that has its basis in the disruption of mental process. "In humans, DLX5/6 expression is under the control of regulatory sequences spanning over 1 Mb on chromosome 7 (7q21.3); this region includes several enhancers that have been linked to somatic and/or mental disorders, including cognitive and social defects." (PMID 39120293, 2024).
Micrognathia (1 paper, 2014). Developmental hypoplasia of the mandible. "Hearing loss and craniofacial defects including cleft palate and micrognathia have been observed in the deletion of a DLX5 and DLX6 enhancer region." (PMID 24699068, 2014).
myeloid neoplasm (1 paper, 2020). Proliferation of myeloid cells originating from a primitive stem cell. "By targeted bisulfite sequencing and RT‐qPCR, we further confirmed that DLX5 hypermethylation was a common event in myeloid neoplasms, and could see as a potential biological marker used in predicting disease prognosis in AML and MDS." (PMID 32508046, 2020). "Collectively, our findings demonstrated that DLX5 methylation, negatively correlated DLX5 expression, was a potential prognostic and predictive indicator in patients with AML and MDS, which could also act as an epigenetic driver in myeloid neoplasms." (PMID 32508046, 2020). "In summary, our findings demonstrated that DLX5 methylation, negatively correlated DLX5 expression, was a potential prognostic and predictive indicator in patients with AML and MDS, which could also act as an epigenetic driver in myeloid neoplasms." (PMID 32508046, 2020).
neuroblastoma (1 paper, 2015). Neuroblastoma (NB) is the most common solid, extracranial childhood tumor. "myc-tagged version of either the WT or the Q178P mutant DLX5 were expressed in the SH-SY5Y human neuroblastoma cells, which express DLX5, miR-9 and miR-200 endogenously." (PMID 25937343, 2015).
Obesity (1 paper, 2012). Accumulation of substantial excess body fat. "Maged1 is a transcriptional co-activator that has been implicated in the regulation of myogenic differentiation, sexual behavior, obesity and the transcriptional function of Dlx5, a positive regulator of osteoblast differentiation and bone mass." (PMID 23300464, 2012).